IL1B (interleukin 1 beta)
Diseases named in the same sentence as IL1B in open-access papers (continued):
Sharing a sentence is not in itself a finding about the gene and the disease.
anemia (continued). "The ACBS encompasses both neutrophilia and lymphopenia, along with anaemia and CRP, and would thus be expected as the best reflection of the IL-1β." (PMID 35027001, 2022). "A similar improvement in anemia was recently demonstrated in FMF-KI mice upon deletion of gasdermin D, a pore-forming protein required for IL-1β release." (PMID 36494621, 2022). "Similar results were observed in models further adjusting for anemia, educational level, and LTBI for IL-1β (aOR, 1.52; 95% CI, 1.15-2.01) and IL-17A (aOR, 2.36; 95% CI, 0.99-5.64) (eTable 1 in the Supplement)." (PMID 34935918, 2021). "The odds ratios (ORs) and 95% confidence intervals for elevation (top quartile) of IL-1α, IL-1β, IL-6, IL-8, and CRP in umbilical cord blood are shown for maternal nutrition (anthropometrics and anemia) and infections in pregnancy." (PMID 34836049, 2021). "In contrast, administration of P2D7KK, an anti-IL1b monoclonal antibody, to CKD mice results in a lower grade of systemic inflammation, better renal function and blunted anemia." (PMID 33737665, 2021). "Many HLH-related and MCMV-induced cytokines are known to suppress hematopoiesis, amongst which IL-1β, IFN-γ and TNF-α, whereas IL-6 has the potency to specifically induce anemia." (PMID 29258535, 2017). "Senkyunolide I may interact with MAPK1, IL-1β, and TNF-α, which were also involved in anemia and vascular systems." (PMID 29551975, 2018). "Relatively high odds ratios were observed for IL-1β (OR = 72.374, 95%Cl 19.688–354.366) and peripheral blood mononuclear cells CD34 (OR = 3.264, 95%Cl 1.263–8.747) and CD38 (OR = 4.398, 95%Cl 1.701–11.906), which together indicates a higher probability of developing anemia." (PMID 37240288, 2023). "In conclusion, we report that IL-1β over-secretion caused by activated NLRP3 inflammasome in myeloid cells, but not mesenchymal cells, drives anemia, and hypoxia in the bone environment, ultimately promoting chondrocyte death, and the development of abnormal growth plate and epiphysis." (PMID 28687790, 2017). "The observation that an inflammatory state compromises therapy of anemia in MDS patients is not new and could be also demonstrated for tumor necrosis factor-alpha and IL-1β in the context of ESA treatment." (PMID 33302451, 2020).
chorioamnionitis (57 papers, 2009 to 2025). A morphologic finding indicating inflammation of the fetal sac membranes. "Increasing levels of infection-mediated pro-inflammatory cytokines, including TNF, IL-1β, IL-6, and IL-2, have been linked to chorioamnionitis and adverse pregnancy outcomes." (PMID 38877443, 2024). "In this context, it has been shown that the presence of IL-1β and IL-6 is responsible for preterm birth associated with chorioamnionitis and weakens the fetal membrane by generating metalloproteases that degrade the extracellular matrix." (PMID 38534983, 2024). "This study unveils a key role for IL-1β, a major mediator of chorioamnionitis, in causing sustained ocular inflammation and perinatal vascular eye injury, and highlights the efficacy of antenatal 101.10 to suppress deleterious inflammation." (PMID 30089839, 2018). "While increased IL-1β has been associated with chorioamnionitis, fetal injury, and preterm birth, mechanistic insight into microbial factors that trigger inflammasome activation and the consequence on fetal injury and preterm birth was not known." (PMID 25750210, 2015). "Our analysis included inflammatory mediators reported to be associated with chorioamnionitis, preterm labor, and fetal inflammatory response syndrome such as IL-1α, IL-1β, IL-6, TNF-α, S100A8, and S100A9." (PMID 22952869, 2012). "Chorioamnionitis-exposed infants with respiratory distress exhibit an altered lung surfactant lipidome compared to unexposed infants.Chorioamnionitis is associated with increased IL-1β in bronchoalveolar lavage fluid and serum from affected infants." (PMID 36994431, 2023). "Also, we previously reported that IL-1β and IL-6 are responsible for chorioamnionitis-associated PTB and weakened fetal membrane through intense generation of extracellular matrix degrading metalloproteases." (PMID 35464466, 2022). "Intra-amniotic infections, such as funisitis or chorioamnionitis, are associated with higher levels of inflammatory cytokines, such as tumor necrosis factor alpha (TNFα) and interleukins (IL), including IL-1beta (IL-1b), IL-6, and IL-8 in amniotic fluid, cord blood, and newborn blood samples." (PMID 35626879, 2022). "Additionally, placental tissues from chorioamnionitis-affected deliveries presented with a seventeen-fold increase in IL-1 abundance compared to healthy pregnancies, with a predisposition towards greater placental IL-1β compared to IL-1α." (PMID 36994431, 2023). "Furthermore, evidence from animal models support that elevation of IL-1β in the fetal-maternal environment may be an important factor in the pathogenesis of preterm labor associated with intra-amniotic infection." (PMID 26446923, 2015). "Elevated levels of cord blood proinflammatory cytokines (IL‐1β, TNFα, and IL-6) have also been associated with preterm birth, one of the most common causes of neonatal morbidity and mortality, as well as chorioamnionitis, brain white matter damage, and chronic lung disease in preterm infants." (PMID 20940111, 2011). "To investigate the effect of BD2 on the amniotic membrane in patients with chorioamnionitis, we compared the levels of inflammatory cytokines, including IL-6 and IL-1β, and anti-inflammatory cytokines such as IL-10 between the patient and normal groups." (PMID 40076749, 2025). "In in vitro studies, ureaplasma had similar upregulate effects in TNFα, IL-1β, IL-6 and IL-8, which were commonly associated with PROM or chorioamnionitis." (PMID 38570745, 2024). "IL-1β is recognized as a key cytokine in human and other animal models which is involved in chorioamnionitis related preterm birth." (PMID 37475854, 2023). "Increased production of IL-1β in both the mother and fetus during chorioamnionitis has been reported by multiple studies, including in amniotic fluid, placenta and chorioamniotic membranes, the umbilical cord in the case of funisitis and in maternal serum." (PMID 36769133, 2023).
chorioamnionitis (continued). "In humans, infants from pregnancies complicated by chorioamnionitis have elevated IL-1β in bronchoalveolar lavage fluid and serum." (PMID 36994431, 2023). "Histological chorioamnionitis has been correlated with increased cord blood IL-1β and IL-6, increased heart rate and decreased blood pressure in the first week after birth." (PMID 36994431, 2023). "In chorioamnionitis, IL-1β abundance was shown to be increased in maternal and fetal tissues, particularly in the amniotic fluid, placenta, maternal blood as well as cord blood in some instances." (PMID 36994431, 2023). "In maternal serum, IL-1β was elevated in preterm histological chorioamnionitis, term clinical chorioamnionitis and PPROM complicated by chorioamnionitis." (PMID 36994431, 2023). "TH, OSI, IL-1b, IL-6, and IL-8 concentrations were higher in the funisitis group than in the chorioamnionitis and control groups." (PMID 35626879, 2022). "The higher expression of Gal-3 and IL-1β in these tissues in the PTB group with chorioamnionitis was accompanied by the higher serum levels of the markers of inflammation, fibrinogen, CRP, and the leukocyte number in the maternal and fetal blood at delivery." (PMID 36362749, 2022). "However, IL-1β was also reported as the first cytokine that plays a role in preterm labor that is associated with intra-amniotic infections, and the cytokine that has been administered to mice systemically and intra-amniotic to Rhesus Monkeys induced chorioamnionitis and preterm labor." (PMID 36362749, 2022). "In the funisitis group, the concentrations of inflammatory cytokines, including IL-1b, IL-6, and IL-8, were significantly higher than in the chorioamnionitis and control groups." (PMID 35626879, 2022). "The biological mechanism behind placental inflammation in RDS stems from increased amounts of interleukin-1 beta (IL-1β) in chorioamnionitis." (PMID 34884395, 2021). "Several characteristic features of human chorioamnionitis are recapitulated in these models, including neutrophilic infiltration in the placental membranes and elevated IL-1β and TNFα in the amniotic fluid." (PMID 32636848, 2020). "IA injections of LPS and IL-1β in mice and rat as well as endocervical injection of E. coli have been used to induce chorioamnionitis in mice." (PMID 32636848, 2020). "Monocytes from chorioamnionitis-exposed term infants with increased H3K4me3 modifications produced less IL-1β, IL-6, and IL-8 when stimulated with LPS." (PMID 32636848, 2020). "A previous study has shown that upregulation of G-CSF in chorio-decidua during chorioamnionitis is IL-1β dependent." (PMID 33193360, 2020). "The recognition of PAMPs during intra-amniotic infection (e.g., chorioamnionitis) leads to up-regulation of TLRs and release of pro-inflammatory IL-1β from immune cells." (PMID 33415098, 2020). "During chorioamnionitis, the concentration of inflammatory mediators including IL-1β, IL-6, IL-8, MMP9 and TNFα in the amniotic fluid increases dramatically." (PMID 32636848, 2020). "Increased levels of IL-1β have a detrimental effect on pregnancy, leading to complications such as chorioamnionitis, preeclampsia, and preterm birth 47-50." (PMID 32410829, 2020). "A further limitation was that we were unable to assay other inflammatory proteins that are generally considered to be the most relevant in intra-amniotic infections, such as IL-1β, IL-10, IL-18, and MMPs, because of limited research funding available." (PMID 29979758, 2018). "Another study also demonstrated that women in the lowest quartile of cervical concentrations of IL-1β and IL-8 early in pregnancy were significantly more likely to subsequently experience chorioamnionitis than women in higher quartiles." (PMID 28296959, 2017). "Specifically, elevation of pro-inflammatory cytokines/chemokines such as IL-1β, Il-6, IL-8 and TNF-α within the AF and fetal membranes have been associated with preterm delivery and chorioamnionitis." (PMID 22253806, 2012).
chorioamnionitis (continued). "C57BL/6 infected animals predominantly exhibited mild to moderate chorioamnionitis (P<0.0001), and a significant reduction in placental expression of IL-1α, IL-1β, IL-6, TNF-α, S100A8, and S100A9 compared to sham controls (P<0.02)." (PMID 22952869, 2012). "Disease outcome was assessed by microbial culture, in situ detection of U. parvum in fetal and utero-placental tissues, grading of chorioamnionitis, and placental gene expression of IL-1α, IL-1β, IL-6, TNF-α, S100A8, and S100A9." (PMID 22952869, 2012). "Furthermore, IL-1β is a potent inhibitor of decidual cell progesterone receptor expression, leading to chorioamnionitis." (PMID 38534983, 2024). "In addition to infection-induced chorioamnionitis, sterile inflammation also exists in the fetal membranes in normal parturition with increased expression of pro-inflammatory cytokines including IL-1β and TNF-α." (PMID 39290694, 2024). "IL1B mRNA in maternal blood was elevated in women with chorioamnionitis complicated by PPROM." (PMID 36994431, 2023). "S100a8, S100a9, Il1b, and Mmp8 have been strongly associated with fetal inflammatory response syndrome (FIRS), preterm labor, and chorioamnionitis in preterm infants, further supporting our rat model using IA LPS injections to simulate IAI and a FIRS-like response." (PMID 38481391, 2023). "In addition, IL-1β is a potent inhibitor of decidual cell progesterone receptor expression, which accompanies chorioamnionitis." (PMID 35464466, 2022). "A previous study reported an increased NLRP3 expression in the chorioamnion membranes in PTB, which was accompanied by an increased inflammasome activation and an increased expression of the mature form of IL-1β in spontaneous preterm labor with chorioamnionitis." (PMID 36362749, 2022). "Also, ampicillin treatment of GBS infection in a rat model of chorioamnionitis increased IL-1β and polymorphonuclear infiltration, which are thought to affect fetal neurodevelopment." (PMID 34925062, 2021). "In the present study, an injection of IL-1β sufficient to induce chorioamnionitis and fetal inflammatory response did not cause skin inflammation in the non-human primate." (PMID 28957335, 2017). "The elevation of IL-1β in the PVWM at 16 and 48 h after IA LPS may be especially important in the pathogenesis of white matter injury associated with chorioamnionitis." (PMID 27596440, 2016). "Furthermore, IL-1β, IL-6, and IL-8 concentrations are increased in maternal plasma women with preterm premature rupture of the membranes and chorioamnionitis." (PMID 25741339, 2015). "Antenatal exposure to cytokines, interleukin-6 [IL-6], interleukin-8 [IL-8], tumor necrosis factor-alpha [TNF-a], interleukin-1beta [IL-1b], is a risk factor for developing BPD and might predispose the subset of neonates exposed to chorioamnionitis prenatally to the development of BPD." (PMID 39795932, 2024). "Previous studies found that IL-1β induced MCP-1 expression in human cells via both NF-κB-mediated and alternative signaling pathways, while significantly increased MCP-1 concentration in the AF of women were associated with evidence of intra-amniotic infection." (PMID 34559862, 2021). "Both VEGF and neuropilins (but not Flt-1 and KDR2) were upregulated after stimulation with IL-1β, which provided an explanation for how an intra-amniotic infection might increase the risk of placental abruption." (PMID 34205566, 2021). "It is tempting to speculate as to why 10 ug of IA IL-1β failed to elicit skin inflammation in the macaque fetus, despite being associated with pulmonary inflammation and chorioamnionitis." (PMID 28957335, 2017). "We performed targeted analyses utilising Random Forest Algorithm of the same eight cfRNA targets (IL1α, IL1β, IL6, IL8, IL10, IL18, CD14, TNFα) used in the chorioamnionitis study." (PMID 40464837, 2025).
chorioamnionitis (continued). "Chorioamnionitis often occurs following PROM, and increased production of IL-1β in chorioamnionitis is a major contributor to tight junction destruction in placental tissues." (PMID 36769133, 2023). "We measured placental IL-1β, given that it is a key mediator of the pro-inflammatory response in GBS-induced chorioamnionitis." (PMID 35563368, 2022). "An elevated level of cytokines IL-1β, IL-6, TNFα, IFNγ, EGF, MIP3α in patients with PROM and intra-amniotic infection." (PMID 34745106, 2021). "In the amniotic fluid, levels of IL-1β, IL-6, IL-8, TNFα, CCL3, 4, and 5 are elevated in women with threatened PTL, especially in the presence of intra-amniotic infection, as are IL-1β, IL-6, IL-8, TNFα, and CCL2 in the cervical fluid." (PMID 25741339, 2015). "Elevated concentrations of IL-1β, IL-6, IL-8, and TNF-α are usually found within the amniotic fluid of patients with chorioamnionitis and/or funisitis." (PMID 22952869, 2012). "Similarly, in the chorioamnionitis-induced PTB rat model, LPS administration increased cerebral expression of inflammatory and apoptotic markers, such as IL-1β, TNF-α, RANK, and caspase-8." (PMID 41009000, 2025). "We first assessed IL-1β expression in myometrial biopsies from normal pregnancy (NP) at term nonlaboring, term laboring and from patients with chorioamnionitis (CA)." (PMID 38378749, 2024). "Premature infants born to mothers with chorioamnionitis presented with elevated pulmonary IL-1β in tracheal aspirates when compared to infants that had spontaneous preterm birth without chorioamnionitis." (PMID 36769133, 2023). "We previously reported that this 1-mg IA injection of E. coli LPS or interleukin 1 beta (IL-1β) in pregnant noninstrumented rhesus macaques caused IUI but not PTL, with characteristics that phenocopied human chorioamnionitis." (PMID 34495952, 2021). "Conversely, severe protracted chorioamnionitis with cellular necrosis was the predominant lesion phenotype in BALB/c mice, which also exhibited a significant increase in placental expression of IL-1α, IL-1β, IL-6, TNF-α, S100A8, and S100A9 (P<0.01)." (PMID 22952869, 2012). "IL-1β was not evaluated in our model since BALF levels were increased rather than decreased after chorioamnionitis in our cohort (unpublished observations), arguing against its contribution to the decreased wound healing ability of BALF." (PMID 19930634, 2009). "Increased lung compliance and improved lung functionality are seen in fetal rabbit and lamb models of chorioamnionitis, as well as after intra-amniotic injection with IL-1α.In murine models, BPD is precipitated by a rise in pulmonary inflammation, and IL-1β plays a key role in its pathogenesis." (PMID 36994431, 2023). "In vivo, a “cocktail” of certain stimuli including bacterial LPS, as a primary and early stimulus, as well as pro-inflammatory, airway-cell-produced cytokines like IL-1β and TNF-α as a secondary stimulus, could be responsible for the synthesis of A20 in the lung in the chorioamnionitis model." (PMID 35096271, 2022). "Thus, in our chorioamnionitis model, A20 may regulate TLR-induced airway inflammation accompanied by a reduction of IL-1β, IL-6, IL-8, and TNF-α." (PMID 35096271, 2022). "Targeted analysis of IL1 A, IL1B, IL6, and CD14 in maternal plasma of the 2 d Sterile Chorioamnionitis Group animals did not improve predictive values with a mean AUC of 0.46 (95% CI 0.13–0.79), Sensitivity 67%, Specificity 57%, PPV 0.67, NPV 0.57." (PMID 40464837, 2025). "In this study, we have shown that there are significantly higher expression levels of Gal-3 and IL-1β in the decidua, fetal membranes, and villi in the PTB group with chorioamnionitis in comparison with the TB group without chorioamnionitis." (PMID 36362749, 2022). "In our study, differences in IL-1β, IL-6 and IL-8 expression did not correlate with ureaplasma CFU/mL or gram of tissue, or the severity of histological chorioamnionitis." (PMID 22253806, 2012).
chorioamnionitis (continued). "However, corresponding elevated maternal plasma markers of inflammation (IL-1β, IL-2, IL-6, IFN-γ and TNF-α) have not been shown to be accurate for the diagnosis of chorioamnionitis." (PMID 40464837, 2025).